KRT17 (keratin 17)
Diseases named in the same sentence as KRT17 in open-access papers (continued):
Sharing a sentence is not in itself a finding about the gene and the disease.
inflammatory skin disease (3 papers, 2021 to 2024). Inflammatory skin disorders covers a broad category that includes many conditions ranging in severity, from mild itching to grave medical health complications These disorders are common in people of all ages and races. "Keratin 17 (K17) is a cytoskeletal protein inducible under stressful conditions and regulates multiple cellular processes, especially in skin inflammatory diseases; however, knowledge regarding its contribution to ACD pathogenesis remains ill defined." (PMID 35178048, 2022).
kidney cancer (3 papers, 2019 to 2022). Primary or metastatic malignant neoplasm involving the kidney. "The multiple functions of KRT17 in kidney cancers unequivocally delineates papillary RCTs and conventional RCCs with distinct natural history, which should be taken into account in clinical managements and therapy." (PMID 31602265, 2019). "However, the possible involvement of KRT17 in the biology of kidney cancer is not yet known." (PMID 31602265, 2019).
liver fibrosis (3 papers, 2020 to 2024). "The overexpression of KRT17 induces the proliferation, migration, and activation of hepatic stellate cells by increasing TGF-β signaling in liver fibrosis." (PMID 39273539, 2024). "Upregulated KRT17 promotes hepatic stellate cell (HSC) activation, which is a potential therapeutic target in liver fibrosis." (PMID 36532504, 2022). "It has been reported that KRT17 is a downstream factor of TGF‐β1 and that ITGBL1 may stimulate liver fibrosis through regulating the TGF‐β1 signalling pathways." (PMID 32537856, 2020).
lung disease (3 papers, 2020 to 2025). "Our analysis revealed CLAD-specific cellular subsets including Fibro.AT2 cells, exhausted CD8+ T cells, and superactivated macrophages while suggesting that pathogenic keratin 17–positive, keratin 5–negative (KRT17+KRT5−) cells represent a common fibrotic mechanism across fibrotic lung diseases." (PMID 41122970, 2025). "Further investigation into what causes the dysplastic nature of KRT5−/KRT17+ cell state could lead to new approaches for treating lung disease." (PMID 38182591, 2024). "Nevertheless, these results suggest that loss of SOX2 may contribute to Wnt activation and TP63 expression in KRT5−/KRT17+ dysplastic cells of IPF and pathological remodeling in human lung disease." (PMID 38182591, 2024).
metastatic tumor (3 papers, 2019 to 2024). "In previous studies, KRT17 has been reported as associated with the development of metastatic disease, MHC type II receptor activity and angiogenesis." (PMID 37669321, 2023). "This indicates that the KRT17 gene plays an important role as tumor suppressor gene in early-stage cancer, and that loss may further promote the development of aggressive, metastatic disease." (PMID 37669321, 2023). "To estimate the role of KRT17 in postoperative tumor relapse, we set up a Cohort of 692 patients without metastatic tumor at the time of operation." (PMID 31602265, 2019).
non-small cell lung carcinoma (3 papers, 2020 to 2022). A group of at least three distinct histological types of lung cancer, including non-small cell squamous cell carcinoma, adenocarcinoma, and large cell carcinoma. "Another study found that the overexpression of KRT17 is associated with the proliferation and invasion and related to poor survival of non-small cell lung cancer patients." (PMID 36010616, 2022).
oral epithelial dysplasia (3 papers, 2017 to 2022). "Recently, the diagnostic utility of the immunohistochemical markers cytokeratin 13 (CK13) and cytokeratin 17 (CK17) has been established for oral epithelial dysplasia." (PMID 30187167, 2018).
oral lichen planus (3 papers, 2020 to 2025). Oral lichen planus is a chronic inflammatory oral condition of unknown aetiology characterized by T-cell-mediated chronic immune response and abnormal epithelial keratinization cycle. "Notably, KRT17 protein was overexpressed in the epithelial layer of OLP, and enriched in antigen processing and presenting pathway, suggesting that KRT17 may amplify inflammatory responses as an antigen in oral lichen planus." (PMID 40574847, 2025). "In a study of oral lichen planus (OLP) and normal skin tissues performing RNA-seq, molecules related to wound healing, KRT17, IL36G, TNC and TGFBI genes were significantly upregulated in OLP tissues." (PMID 37929023, 2023).
autoimmune disease (2 papers, 2022 to 2025). A disorder resulting from loss of function or tissue destruction of an organ or multiple organs, arising from humoral or cellular immune responses of the individual to their own tissue constituents. "Stress keratin 17 (K17) is a stress-induced keratin expressed in epithelial cells under conditions such as wound healing, inflammation, and autoimmune diseases." (PMID 41462954, 2025).
basal cell carcinoma of the skin (2 papers, 2016 to 2024). "Krt5-Gli2 transgenic mice develop multiple basal cell carcinomas of the skin that are characterized by robust expression of KRT17 in the tumor cells." (PMID 27512993, 2016).
cervical tumor (2 papers, 2018 to 2020). "Some studies of skin and cervical tumours indicated that keratin 17 has a role in the cell cycle and in gene expression regulation." (PMID 31809668, 2020).
endometrial cancer (2 papers, 2022). Primary or metastatic malignant neoplasm involving the endometrium (mucous membrane that lines the endometrial cavity). "In patients with high-grade endometrial cancer, high expression levels of KRT17 mRNA was associated with decreased OS, with a median survival of 4.2 years for high expression of KRT17 mRNA and 9.2 years for low expression of KRT17 mRNA." (PMID 35281081, 2022). "Studies have shown that KRT17 protein is an independent prognostic biomarker in patients with high-grade endometrial cancer." (PMID 35281081, 2022).
epidermolysis bullosa simplex (2 papers, 2012 to 2018). Epidermolysis bullosa simplex (EBS) is a group of hereditary epidermolysis bullosa (HEB) disorders characterized by skin fragility resulting in intraepidermal blisters and erosions that occur either spontaneously or after physical trauma. "In fact, sulforaphane, a chemical activator of Nrf2, restores skin integrity in an epidermolysis bullosa simplex model (created by Krt5 or Krt14 mutation) by activating Krt17 expression." (PMID 22567161, 2012).
gastric adenocarcinoma (2 papers, 2019 to 2021). "Previous studies have shown that the expression of KRT17 is related to the tumor progression and poor prognosis of gastric adenocarcinoma." (PMID 34935584, 2021). "Recently, many studies report the critical role of KRT17 in many malignancies, including cervical cancer, basal skin tumor, urothelial tumor, pancreatic cancer, and gastric adenocarcinoma." (PMID 34935584, 2021).
infiltrating ductal carcinoma (2 papers, 2022 to 2023). "Patients with infiltrating ductal carcinoma had lower KRT17 expression than patients with infiltrating lobular carcinoma." (PMID 36139022, 2022).
laryngeal carcinoma (2 papers, 2015 to 2022). Carcinoma that arises from the laryngeal epithelium. "Therefore, we still need to strengthen the study of KRT17 in laryngeal cancer mechanism and clarify the pathogenic role of KRT17 in laryngeal cancer." (PMID 35281081, 2022). "The results suggest that KRT17 expression level is highly sensitive and specific in the detection of laryngeal cancer and paracancerous tissues and can be used as a valuable biomarker for LSCC." (PMID 35281081, 2022). "However, the exact mechanism of KRT17 in laryngeal cancer is still unclear." (PMID 35281081, 2022). "It noted up-regulation of S100A2, FGB, KRT17, FN1 and POSTN in laryngeal carcinoma tissues, as compared with normal tissue." (PMID 25874882, 2015).
liver cancer (2 papers, 2022 to 2024). An epithelial or non-epithelial malignant neoplasm that arises from the liver. "Conversely, in cancer types where the expression of the KRT17 signature was relatively low, such as liver cancer (TCGA_LIHC), it did not serve as an indicator of survival." (PMID 38822440, 2024).
liver disease (2 papers, 2022 to 2024). "ANXA2 overexpression and KRT17 nuclear translocation were also observed, supporting the role of both molecules in the progression of liver disease." (PMID 39273539, 2024). "Moreover, recent data suggest that both KRT17 and ANXA2 could be potential biomarkers for the diagnosis of liver diseases." (PMID 39273539, 2024).
oropharyngeal squamous cell carcinoma (2 papers, 2022 to 2024). "The identification of KRT17 as a prognostic biomarker for oropharyngeal squamous cell carcinoma (independent of HPV status) has potential clinical significance." (PMID 35281081, 2022).
pterygium (2 papers, 2013 to 2025). A wedge-shaped fibrovascular lesion arising from the bulbar conjunctiva and extending to the cornea. "Here we investigated the role of IPO13 in the pathogenesis of pterygium and the underlying mechanism including interaction with other cell proliferation–related factors: keratin 17 (K17), a lesional protein and a member of the type I keratins, and c-Jun, a protein of the activator protein-1 complex." (PMID 23559854, 2013). "For example, KRT6A expression is upregulated in pterygium, a benign overgrowth of BC, while KRT17 marks limbal SCs and regulates their stemness, differentiation, proliferation, and immune responses." (PMID 41439999, 2025).
sarcoma (2 papers, 2022). A usually aggressive malignant neoplasm of the soft tissue or bone. "In sarcomas and cancers, although the origin of tumors is different, the expression of KRT17 is still high in sarcomas and cancers." (PMID 35281081, 2022). "Although KRT17 plays an important role in the occurrence and development of sarcomas, the mechanism of KRT17 in different types of sarcomas is still unclear and needs further study." (PMID 35281081, 2022).
squamous intraepithelial lesion (2 papers, 2021 to 2022). "The expression of KRT17 was up-regulated in the high-grade squamous intraepithelial lesion and squamous cell carcinoma (SCC) compared to the normal cervical epithelium and low-grade squamous intraepithelial lesion." (PMID 35281081, 2022).
systemic sclerosis (2 papers, 2021 to 2022). A chronic disorder, possibly autoimmune, marked by excessive production of collagen which results in hardening and thickening of body tissues. "Cytokeratin 17 was independently associated with Ssc disease severity, higher CK17 values being protective for a more active disease." (PMID 36277429, 2022).
thymoma (2 papers, 2022 to 2024). A neoplasm arising from the epithelial cells of the thymus. "KRT6A and KRT17, commonly used markers for the detection of thymoma, were not significantly overexpressed in the malignant cell populations; Only KRT14 was found overexpressed in the malignant mcTEC subpopulation." (PMID 39258580, 2024). "To confirm the difference histologically, we stained KRT6 and KRT17 proteins in thymoma tissue sections and observed the corresponding staining patterns to MG and non-MG-thymoma, respectively." (PMID 35869073, 2022).
ulcers (2 papers, 2023 to 2024). "However, another study showed significant downregulation of KRT17 in chronic nonhealing ulcers in RNA-seq analysis of healing ulcers vs chronic nonhealing venous ulcer tissues, suggesting that downregulation of KRT17 may impede the healing of chronic ulcers." (PMID 38205163, 2024).
bile duct cancer (1 paper, 2024). "Finally, as we investigated the prognostic significance of KRT17, we at first recognized that the high KRT17 expression predicted a worse survival in bile duct cancer (TCGA_CHOL) and linked with the perineural invasion." (PMID 38822440, 2024).
cervical disease (1 paper, 2017). "Statistically significant changes in KDR and SERPINB3 expression, like the known biomarker KRT17, indicate their potential in identifying high-grade cervical disease." (PMID 29021401, 2017). "KRT17 was analyzed as a known biomarker of cervical disease progression." (PMID 29021401, 2017).
clear cell renal cell carcinoma (1 paper, 2019). "Survival analysis of the cancer genome atlas (TCGA) dataset showed for the first time that low gene expression of MARC2, cubilin, and SLC47A1 and high gene expression of KRT17 are associated with poor overall survival in clear cell renal cell carcinoma patients." (PMID 31878355, 2019).
craniopharyngioma (1 paper, 2024). A benign, partly cystic, epithelial tumor of the sellar region, presumably derived from Rathke pouch epithelium. "Keratins, such as KRT19 and KRT17, were consistently expressed, suggesting their potential role as common markers for craniopharyngioma tumor cells." (PMID 39483146, 2024).
dental caries (1 paper, 2018). The decay of a tooth, in which it becomes softened, discolored, and/or porous. "Due to the low number of frequent missense SNPs in KRT16 and KRT17 in our cohorts, the present study did not allow us to make any conclusion on the potential genetic association between variants in these two genes and dental caries experience." (PMID 29357356, 2018).
ductal carcinomas (1 paper, 2007). "Seven differentially expressed genes (KRT5, KRT6 and KRT17 between tumor and normal cells, CDH1, EMP1, DDR1 and DVL1 between lobular and ductal carcinomas) were verified by immunohistochemical detection of proteins on TMA slides comprising of cores from 119 cases." (PMID 17389037, 2007).
eczema (1 paper, 2026). "Notably, keratin 17 (K17) exhibits pathognomonic upregulation in psoriatic lesions, where both mRNA abundance and protein expression are markedly elevated compared to normal skin or eczema tissues." (PMID 41508030, 2026).
emphysema (1 paper, 2021). "KRT17 and DHRS9 were found to take part in the pathogenesis of emphysema." (PMID 34277700, 2021). "However, the mechanism through which canonical and non-canonical WNT signaling pathways interact with KRT17 warrants further studies, and the specific roles of KRT17 in the development of COPD and emphysema are still to be explored." (PMID 34277700, 2021).
hepatoblastoma (1 paper, 2024). Hepatoblastoma (HB) is a malignant hepatic tumor and is the most common pediatric liver cancer. "In this paper, the pathological staining findings of Cytokeratin 17, AFP, Hepatocyte and Glypican 3 in the tumor tissue clearly indicated a fetal epithelial subtype of hepatoblastoma." (PMID 38819760, 2024).
human papillomavirus infection (1 paper, 2022). "KEGG analysis suggested that KRT17 may play a role in tumor pathogenesis following human papillomavirus infection, and the gene ontology enrichment analysis indicated that the carcinogenicity of KRT17 can be attributed to cadherin binding, intermediate fibrocytoskeleton and epidermal development." (PMID 35646078, 2022).
hypertrophy (1 paper, 2024). Hypertrophy is the increase in the volume of an organ or tissue due to the enlargement of its component cells. "Mutations in the KRT17 gene result in alterations in the structure of KRT17, which disrupts the integrity of the epidermis and can lead to the development of genetic disorders of the skin, such as congenital nail hypertrophy and multiple lipodystrophies." (PMID 38205163, 2024).
hypopharyngeal carcinoma (1 paper, 2023). Carcinoma, predominantly squamous cell, arising from the epithelial cells of the hypopharynx. "Most importantly, both high expression of NR120519 and low expression of KRT17 were closely associated with enhanced malignancy and poor prognosis of hypopharyngeal carcinoma." (PMID 36765563, 2023). "RIP and WB assays showed that KRT17 was associated with and blocked by NR120519.The silencing of KRT17 promoted cell proliferation and the migration of hypopharyngeal carcinoma in vitro and cell proliferation in vivo by activating the AKT/mTOR pathway and epithelial-mesenchymal transformation (EMT)." (PMID 36765563, 2023). "NR120519 activated the AKT/mTOR pathway and EMT by blocking KRT17 and promoted cell proliferation and migration of hypopharyngeal carcinoma in vitro and cell proliferation in vivo." (PMID 36765563, 2023). "In summary, this study showed that NR120519 expression was significantly upregulated in hypopharyngeal carcinoma tissues, consistent with the expression of KRT17." (PMID 36765563, 2023). "The objective of the present study was to investigate the potential relationship between NR120519 and KRT17 in hypopharyngeal carcinoma." (PMID 36765563, 2023). "The immunohistochemical study further demonstrated the tumor suppressive function of KRT17, demonstrating that high KRT17 expression was positively connected with the prognosis of patients with hypopharyngeal carcinoma and that KRT17 was substantially expressed in cancer tissues." (PMID 36765563, 2023). "We used lentivirus to knock down KRT17 in the hypopharyngeal carcinoma Fadu cell line." (PMID 36765563, 2023). "However, our experimental results showed the opposite function in hypopharyngeal cancer, indicating the tissue specificity of KRT17." (PMID 36765563, 2023). "Similarly, in hypopharyngeal carcinoma, we found that KRT17 acts as a cancer suppressor gene; this effect may be related to the tissue specificity of KRT17." (PMID 36765563, 2023). "Hence, we hypothesized that NR120519 may act by regulating KRT17 in hypopharyngeal carcinoma." (PMID 36765563, 2023). "We found that the expression of KRT17 and NR120519 was positively and negatively correlated with the prognosis of patients with hypopharyngeal carcinoma, respectively." (PMID 36765563, 2023).
jaw cysts (1 paper, 2020). "OKCs have a typical parakeratotic epithelium demonstrating transepithelial cytokeratin 17 (CK17) and basal bcl2 staining on immunohistochemistry (IHC), which distinguishes them from other common jaw cysts." (PMID 32632899, 2020).
keratosis pilaris (1 paper, 2019). A form of dry skin characterized by hair follicles plugged by scale. "It is tempting to speculate that the increased expression of keratins 10 and 16 may contribute to palmar hyperlinearity and keratin 17 may contribute to keratosis pilaris." (PMID 31641698, 2019).
leiomyoma (1 paper, 2023). A well-circumscribed benign smooth muscle neoplasm characterized by the presence of spindle cells with cigar-shaped nuclei, interlacing fascicles, and a whorled pattern. "The race-associated aberrant expression of KRT17 could thus be of great relevance to fibroid pathogenesis and merits further investigation." (PMID 37686244, 2023). "For comparison of differential expression of genes in leiomyomas, there was a significant race/ethnicity correlation in expression for TNFRSF19, IRS4, PLEKHG4B, PGR, KRT17, CCDC177, MYO5B, and ZNF703." (PMID 37686244, 2023).
lipid metabolism disorder (1 paper, 2023). "Conversely, among the top 10 proteins of HML pattern, four were related to lipid metabolism, including APOA1, KRT17, B2R8I2, and ATP8B3, demonstrating continuously increased lipid metabolism disorder with the increase of bacterial loads." (PMID 37908762, 2023).
liver cirrhosis (1 paper, 2022). "Two diagnostic models including SOCS2, LCAT, FTCD, KRT17, PBK, and CBX2 expression were proved to accurately separate HCC from normal and liver cirrhosis samples in this study." (PMID 36159831, 2022).
metastatic prostate carcinoma (1 paper, 2009). A carcinoma that arises from the prostate gland and has spread to other anatomic sites. "As the full set of genes potentially regulated by this process is unknown, we chose three candidate genes, SNCA, PTGER and KRT17, whose core promoter regions are occupied by H3K27me3, and which have recently been shown to define an epigenetic signature of metastatic prostate cancer." (PMID 19849834, 2009).